SYP (synaptophysin)
Diseases named in the same sentence as SYP in open-access papers (continued):
Sharing a sentence is not in itself a finding about the gene and the disease.
tumor (continued). "These tumor cells were diffusely positive for the neuroendocrine markers synaptophysin and CD56." (PMID 39439633, 2024). "Remarkably, the tumor cells exhibited strong positivity for synaptophysin." (PMID 38926750, 2024). "One tumor showed predominantly neuroendocrine-like aggregates and “Zellballen-like nests) that were initially misinterpreted (together with prominent synaptophysin expression) as unusual extra-adrenal paraganglioma (Case 1), resulting in suboptimal initial therapy recommendation." (PMID 39249507, 2024). "Additionally, the expression of NE marker SYP was reduced in xenograft tumor tissues exhibiting REST overexpression." (PMID 38777812, 2024). "IHC showed the tumour cells positivity for synaptophysin, CD56, PanCK and p16." (PMID 39268326, 2024). "In addition, there is a significant correlation between the expression of synaptophysin and higher tumour stages, the incidence of metastasis, histological grading, and tumour proliferation." (PMID 39036213, 2024). "However, the majority of the tumour had poorly differentiated/neuroendocrine morphology with concordant expression of synaptophysin and high KI67 labelling index." (PMID 40525454, 2024). "In our case, the tumor was positive for synaptophysin and NeuN." (PMID 39399175, 2024). "While areas of the PLAGL1 amplified tumor showed strong positivity for GFAP or synaptophysin, sometimes with overlapping areas of staining, other areas of the tumor were largely negative for both lineage markers with small clusters or occasional cells showing positivity." (PMID 39228008, 2024). "The tumor cells express SYP, CgA, glucagon and often pancreatic polypeptide (PP)." (PMID 36830839, 2023). "Indeed, SCNECs and MCCs are histologically similar, with both tumor types staining for neuroendocrine markers, such as synaptophysin and CgA." (PMID 38137784, 2023). "By immunohistochemistry, the tumor cells expressed synaptophysin, chromogranin, NKX2.2 (diffuse, nuclear), GFAP (patchy), SMI31 (neurofilament) (focal, cytoplasmic), and TdT (diffuse, nuclear), while lacking expression of CD99, TTF-1, CK 20, MCPyV, PHOX2B, Olig2, OCT3/4, CD45, CD3 and PAX5." (PMID 38031161, 2023). "Synaptophysin and chromogranin A immunomarkers were strongly positive in all the tumours." (PMID 38239530, 2023). "However, a histopathological examination revealed a small cell carcinoma, for a high nucleus-to-cytoplasm ratio in the tumor cells, as well as immunohistochemically positive findings for chromogranin A, and synaptophysin." (PMID 37721573, 2023). "Synaptophysin immunoreactivity has been observed for alpha- and beta-cells of the pancreatic islets, as well as for other neuroendocrine cells such as adrenal cortical cells and their tumours." (PMID 36362289, 2022). "Further, in a few cases, the percentage of synaptophysin-positive tumor cells was as low as 5%." (PMID 36401284, 2022). "In contrast, tumor cells were diffusely and strongly labeled by both cytokeratin and synaptophysin." (PMID 35978432, 2022). "The tumor cells showed a strong positivity for synaptophysin and CD56." (PMID 36414742, 2022). "The tumor cells showed small cell morphology with high malignancy and expressed SYP only." (PMID 36033483, 2022). "Immunohistochemical examination of the section indicating solid-nest growth revealed the tumor cells to test positive for synaptophysin, CD56, and partially positive for chromogranin A. The growth had Ki-67 index > 20%, indicating the existence of the NEC component." (PMID 35235080, 2022).
tumor (continued). "Notably, markers of hepatic (Hep Par-1) and neuroendocrine (SYP, CHGA) differentiation were equally retained in the organoids, further underlining their ability to recapitulate the tumor biology in vitro." (PMID 35789568, 2022). "We therefore hypothesized that platelets, derived from patients with neuroendocrine malignancies, might express distinct levels of tumor-specific surface proteins like synaptophysin." (PMID 34064565, 2021). "Even if further work is needed to reveal the role of synaptophysin as a binding partner of synaptobrevin in tumor-educated platelets, an involvement in platelet exocytosis might be speculated." (PMID 34064565, 2021). "No relation was determined between the cut-off value of PLR and tumor localization, histological grade, mitosis, Ki-67 proliferation index, metastasis, lymphovascular invasion, perineural invasion, synaptophysin, and chromogranin A immunohistochemical staining (all p>0.05)." (PMID 34532190, 2021). "Immunohistochemistry showed that these tumor cells were positive for synaptophysin." (PMID 34065573, 2021). "Tumor cells were verified by immunohistochemical staining for synaptophysin, a NEN marker." (PMID 33986468, 2021). "The original tumor and corresponding organoid lines expressed synaptophysin in all three cases." (PMID 33776923, 2021). "Tumor cells were immunopositive for chromogranin, synaptophysin, and S-100." (PMID 34307231, 2021). "In conventional adenocarcinomas with a synaptophysin expression of more than 30% of the tumor cell population, a slightly poorer disease-free survival was noted in univariate analysis, but this result was not confirmed by multivariate analysis including UICC stage, WHO grade, age and gender." (PMID 34680258, 2021). "In the current study, we screened 1002 conventional adenocarcinomas for synaptophysin expression and found that approximately a quarter of these tumors harbored synaptophysin-positive cells, albeit mostly as scattered tumor cells embedded in the epithelium of the neoplastic glands." (PMID 34680258, 2021). "This might indicate a direct link of synaptophysin expression in the tumor and pSyn expression on platelets." (PMID 34064565, 2021). "The expression level of SYP decreased with the increase in the tumor grade." (PMID 34136394, 2021). "However, this tumor occurs mostly in young age and tumor cells are positive for synaptophysin and B-catenin." (PMID 34034720, 2021). "IHC staining for chromogranin A and synaptophysin was also strongly positive in the tumor cells." (PMID 33031286, 2020). "Also staining for the neuroendocrine marker Synaptophysin revealed only single cell reaction at a maximum of < 5% of the tumour cells." (PMID 32483440, 2020). "Neuronal cells were positive for synaptophysin and some tumor cells showing positivity for CD34." (PMID 32451719, 2020). "Moreover, staining of the tumor was positive for chromogranin A and synaptophysin, which are neuroendocrine markers." (PMID 31678698, 2019). "All patient tumours were positive for chromogranin A, synaptophysin, serotonin, SSTR2 and Hsp90." (PMID 30730850, 2019). "Most tumor cells were positive for synaptophysin and the Ki-67 nuclear labeling index was + 1%." (PMID 31727021, 2019). "Most tumor cells were positive for synaptophysin and Ki-67 was approximately 15%." (PMID 31727021, 2019). "Synaptophysin, on the other hand, was positive in most of the tumor cells." (PMID 28980157, 2018). "On immunohistochemical staining, the tumor was positive for chromogranin A and synaptophysin." (PMID 30159830, 2018). "In a cohort of 40 samples, 29 out of 40 IDHwildtype tumours expressed synaptophysin." (PMID 30297697, 2018). "Expression of mature neuronal markers MAP2 and SYP were seen in isolated xenograft tumor cells." (PMID 29774098, 2018). "Immunohistochemically, the tumor cells were positive for synaptophysin, chromogranin A, and CD56." (PMID 28895097, 2017).
tumor (continued). "Bilateralism of the tumours, presence of Reinke crystals and expressions of synaptophysin, Inhibin α, CD56, androgen receptor, DLK1, INSL3, CYP11B1, CYP21A2 and MC2R have all been studied as potential markers, but none of these markers individually can reliably discriminate TARTs from LCTs." (PMID 29038332, 2017). "The tumor cells and lipidized cells of liponeurocytoma may express the neuronal markers such as synaptophysin, NSE and MAP-2." (PMID 28977976, 2017). "Immunohistochemically, the tumor expressed synaptophysin and CD56." (PMID 28706747, 2017). "Tumor cells were positive for chromogranin A, synaptophysin, and CD56." (PMID 28744415, 2017). "The tumour cells were positive for synaptophysin and focally positive for chromogranin A." (PMID 26955490, 2016). "Immunoperoxidase staining for CgA and synaptophysin was positive in all tumor tissues." (PMID 26673010, 2016). "The cytoplasm of tumor cells was strongly positive for synaptophysin, CD56, TTF1, and CK7." (PMID 26801624, 2016). "The viable areas located at the periphery of the tumor contained numerous cells undergoing pyknosis, and the cytoplasm of these tumor cells was immunohistochemically positive for synaptophysin, tyrosine hydroxylase, and chromogranin A. The tumor cell nuclei were positive for SDHB." (PMID 27729064, 2016). "Tumor cells were focally positive for calponin and synaptophysin." (PMID 26187280, 2015). "Immunoperoxidase staining for chromogranin A and synaptophysin was positive in all tumor tissues." (PMID 26124083, 2015). "Immunohistochemically, tumor cells showed a positive and diffuse staining for synaptophysin." (PMID 26374700, 2015). "In addition, D283hCD73 generated a tumor with more differentiated cells, as demonstrated by the enhanced synaptophysin immunoreactivity." (PMID 26491983, 2015). "Furthermore, immunohistochemical staining showed that the tumor cells were synaptophysin- and NeuN-positive and GFAP-negative." (PMID 26376790, 2015). "One case was diagnosed as MANEC, expressing CgA and synaptophysin, tumour grade G3." (PMID 24695372, 2014). "Further studies included immunostaining for nestin with all tumor cells being positive and for synaptophysin showing focally positive tumor cells from all three resections with slightly increased staining in the second tumor sample and larger foci of stained cells in the last resection." (PMID 25563358, 2014). "All G1/G2 tumours displayed strong immunoreactivity for CgA and synaptophysin." (PMID 24695372, 2014). "Histological examination identified multifocal tumour growth composed of poorly differentiated neoplastic cells with densely packed round to oval cells with hyperchromatic nuclei surrounded by scanty cytoplasm and diffuse expression of synaptophysin." (PMID 24460684, 2014). "Immunohistochemically, the tumor cells were positive for synaptophysin and chromogranin A." (PMID 24099520, 2013). "Immunohistochemical expression of CD56, synaptophysin, and chromogranin A was strongly positive in the tumor cells, while CD117, CD30, epithelial membrane antigen (EMA), alpha-inhibin, and Oct-4 nuclear stain were negative, consistent with a neuroendocrine tumor." (PMID 24171129, 2013). "The tumor was immunohistochemically strong staining for synaptophysin and CD56." (PMID 24099413, 2013). "The tumor cells were immunoreactive for chromogranin and synaptophysin." (PMID 22344361, 2012). "At the head and neck unit, our patient underwent a biopsy that showed a cervical lymph node metastasis of a neuroendocrine small-cell carcinoma from pulmonary origin (The immunocytochemical study had demonstrated that tumor cells were positive to synaptophysin, chromogranin, CK7, and TTF1." (PMID 23119202, 2012). "However, there was a significant correlation of the expression of synaptophysin with earlier age to tumor detection and death." (PMID 23304522, 2012). "The TNM classes for these synaptophysin immunopositive tumours were pT1aN0M0 and pT3aN0M0." (PMID 20462442, 2010).
tumor (continued). "On immunohistochemistry, tumor cells were positive for synaptophysin, chromogranin and glucagon." (PMID 20550685, 2010). "In our study, immunostaining for synaptophysin was rare (only 1% of the tumours)." (PMID 20462442, 2010). "The tumor cells stained positively for CK 20, chromogranin, and synaptophysin." (PMID 20300432, 2010). "Two of the tumours (1%) were immunopositive for synaptophysin." (PMID 20462442, 2010). "In our case the tumor was positive to synaptophysin and NSE, which confirmed the diagnosis." (PMID 21087512, 2010). "The tumor cells were positive for neuroendocrine markers chromogranin A and synaptophysin." (PMID 20591162, 2010). "The tumor cells showed positive reactivity for synaptophysin, somatostatin, and CD56." (PMID 20444291, 2010). "Tumor cells usually stain positive with chromogranin, synaptophysin and neuron-specific enolase." (PMID 19014620, 2008). "Diagnosis is established by the characteristic silver affinity of the tumor cells, the ultrastructural occurrence of neurosecretory granules, and immunohistochemically detectable markers, including neuron-specific enolase, chromogranin, and synaptophysin." (PMID 18211708, 2008). "Histologically, the tumor displayed mild cytologic atypia, abundant necrosis, and intravascular metastases, the last feature of which was identified by immunohistochemical markers for chromogranin and synaptophysin." (PMID 17626622, 2007). "Further HPE revealed the tumor to be a retroperitoneal paraganglioma because not only did the tumor cells appeared as spindle-shaped cells clustered with the sustentacular cells into small nests, but they were also immunoreactive toward chromogranin, synaptophysin, and CD56." (PMID 39703846, 2024). "The immunohistochemical characterization of tumor tissue revealed the presence of typical syncytial arrangement of undifferentiated cells, poorly differentiated embryonal cells with hyperchromatic and variably shaped nuclei and diffused expression of synaptophysin." (PMID 38612726, 2024). "Some tumor sections were immunostained with ready-to-use primary antibodies against broad-spectrum cytokeratin (CK), vimentin, calretinin, Wilms tumor gene-1 (WT-1), D2–40, Paird box 8, synaptophysin, chromogranin-A, inhibin-α, S-100, Melan-A, HMB45, CD34, and Ki-67 (Maixin, Fuzhou, China)." (PMID 38115250, 2023). "Moreover, the evaluation of tumor sections immunostained for nestin and synaptophysin showed that GL261 parental tumors were characterized by a sharp boundary between the neoplastic mass and normal healthy parenchyma, with a more invasive pattern of growth than that observed in GL261-CIITA tumors." (PMID 36993983, 2023). "Among the significantly upregulated proteins in JunBlo microglia cells we found the proteins: Rheb, synaptophysin, and KEAP1, which are reported to be associated with inflammatory response, and therefore may facilitate tumor-restraining properties in JunBlo microglia." (PMID 37894348, 2023). "The tumor can stain positive for synaptophysin in 75% of NECs, followed by chromogranin A. In cases of functional NEC, urine 5-hydroxyndoleacetic acid and nuclear imaging studies, such as somatostatin scintigraphy or MIBG, may be useful for diagnosing and evaluating the therapeutic response." (PMID 35653037, 2022). "Also, neuroendocrine differentiation, defined by cytoplasmic argyrophilia and/or immunoreactivity to markers such as chromogranin, synaptophysin and neuronal-specific enolase, might be present within the tumor." (PMID 33707745, 2021). "Notably, quite a few tumor types may exhibit focal or diffuse SYP immunoreactivity, including adenocarcinomas of various origin, malignant melanoma, sarcomas and adrenal cortical tumors." (PMID 34571751, 2021). "In addition, serum SYP concentrations increased in correlation with the LnNE tumor volumes." (PMID 28978002, 2017).
tumor (continued). "The final pathology report described a 9-cm tumor, composed of well-defined nests of cuboidal cells separated by vascular fibrous septa, having a classic zellballen appearance, with lymphovascular invasion; immunohistochemistry was positive for synaptophysin and chromogranin." (PMID 24138700, 2013). "Synaptophysin positivity in RCC may be associated with good prognosis, but as an uncommon phenomenon, this observation should be further studied with large number of RCC tumours." (PMID 20462442, 2010). "Interestingly, the prognosis of patients with synaptophysin immunopositive tumours was excellent." (PMID 20462442, 2010). "A small minority of tumor cells were convincingly positive for HMB45, and rare cells stained with SALL4, CD117, glypican‐3, myogenin, desmin, and synaptophysin." (PMID 40610013, 2026). "At the protein level, organoids expressed both stem/progenitor markers (nestin, vimentin, SOX10) and chromaffin differentiation markers (synaptophysin, CD56), although expression of the latter was markedly reduced compared to primary tumor tissue." (PMID 41928881, 2026). "Diagnosis was confirmed through histopathology and immunohistochemistry (IHC), including synaptophysin, INSM1, and a Ki-67 index near 100%, consistent with a highly proliferative tumor and aggressive biologic behavior." (PMID 42255800, 2026). "The tumour showed diffuse staining for the following immunohistochemical (IHC) markers: GATA‐3, CD56, synaptophysin, chromogranin, alpha‐methylacyl CoA racemase (P504S), and vimentin." (PMID 40588841, 2025). "Representative sellar tumor samples displayed immunoreactivity for pituitary NET markers, such as chromogranin A, synaptophysin, S100, and CD56/NCAM36,41,42." (PMID 41203869, 2025). "Histologically, our patient’s tumor demonstrated the classic morphology of CPP but with expanded immunophenotypic features, most notably membranous synaptophysin positivity." (PMID 41220478, 2025). "In the case presented, immunohistochemistry demonstrated solid and diffuse staining for synaptophysin and INSM1, along with a remarkably high Ki-67 proliferation index approaching 100%, thus indicating an aggressive tumor with high metastatic potential." (PMID 41333490, 2025). "In our case, the tumor exhibited positive staining for CK5/6, P40, P63, and CK7, while showing negative staining for Napsin A, TTF-1, CD56, Chromogranin A, Synaptophysin, Pax-8, thyroglobulin, and vimentin." (PMID 40061900, 2025). "In total, 129 (59%) tumours showed evidence of NED, defined as immunohistochemical expression of synaptophysin or chromogranin‐A, while 40 (18%) showed evidence of NED and expressed serotonin." (PMID 39526928, 2025). "In contrast, immunohistochemical staining of SCCOPT tumor tissues generally shows positive staining for chromogranin A, CD56, synaptophysin, and neural-specific enolase." (PMID 40071085, 2025). "Daily oral administration of HOC in a nude mouse NEPC xenograft model markedly suppressed the tumor expression of EPHA3 and BRN2, along with their downstream effectors EZH2, ASCL1, and DLL3 and neuroendocrine markers SYP and CHGA." (PMID 41514539, 2025). "Both SYP and CHGA, markers of differentiated chromaffin cells, showed weaker staining in organoids compared to the primary tumor tissue." (PMID 40576438, 2025). "Immunophenotyping: tumor cells were diffusely strongly positive for P16, and expressed 2 or more neuroendocrine markers, with positive rates of CD56 100% (4/4), synaptophysin (SYN) 100% (4/4), and chromogranin (CgA) 50% (2/4)." (PMID 41305788, 2025). "The tumor cells exhibited positive expressions for the epithelial cell markers AE1/AE3, along with the neuroendocrine markers, synaptophysin (Syn), chromogranin (CgA), and CD56 as based on results from immunohistochemical staining." (PMID 40666092, 2025).